ALB (albumin)
Diseases named in the same sentence as ALB in open-access papers (continued):
Sharing a sentence is not in itself a finding about the gene and the disease.
diabetes (continued). "Based on different multivariable models including age, serum albumin, hemoglobin, ferritin and TSAT, we found that hemoglobin, ferritin, serum albumin and age were independent factors associated with all-cause mortality in patients without diabetes." (PMID 36719878, 2023). "DM: diabetes mellitus; HbA1c: hemoglobin A1C; Urine ACR: urine albumin creatinine ratio; TG/HDL: triglycerides/high-density lipoprotein; LDL-C: low-density lipoprotein cholesterol." (PMID 37398707, 2023). "Studies reported by Chen and others have shown that diabetes is a risk factor for PDAP, and that PDAP is correlated with gender, with male individuals, lower serum albumin levels, gram-negative bacteria, and multiple microbial infections being at higher risk of treatment failure." (PMID 37550622, 2023). "Both the body mass index and e24UNa/Cr positively correlated with the urinary albumin/creatinine ratio (both, P < 0.001), and had a synergistic effect on increasing urinary albumin/creatinine ratio independent of age, sex, mean arterial pressure, and diabetes (interaction P = 0.04)." (PMID 37587243, 2023). "Albumin is closely related to the metabolism, biosynthesis, and transport of cholesterol, and serum albumin levels may affect the prognosis of different levels of LDL-C in patients with diabetes." (PMID 36643628, 2023). "Furthermore, albumin is an important factor in the GNRI equation and therefore may potentially explain the relationship between GNRI and mortality in persons with diabetes." (PMID 37127636, 2023). "For example, if an adult with hypertension is 55 years old, has a monocyte count of 0.5 × 10^9/L, a lymphocyte count of 10 × 10^9/L, albumin of 40 g/L, a serum potassium concentration of 4 mmol/L, cardiovascular disease, no diabetes mellitus, a creatinine of 400 μmol/L, and an HbA1C of 5%." (PMID 38074152, 2023). "Adjuvant chemotherapy improved OS in the majority of the subgroups, regardless of age group, gender, any history of diabetes, serum albumin level, and eGFR level; however, patients with CCI ≥ 8 (HR: 1.17, 95% CI: 0.93–1.47, p = 0.168) did not benefit from adjuvant chemotherapy." (PMID 37568584, 2023). "The relationship between serum calcium and retinopathy prevalence remained significant after excluding participants with pre-diabetes, history of cardiovascular disease, or those without a normal reference range of serum calcium, as well as substituting total calcium for albumin-corrected calcium." (PMID 36531449, 2022). "In this investigation, we discovered that dengue patients with diabetes had lower serum albumin levels (0.69 ± 0.07) g/dl and platelet counts (49.758 ± 3.349) × 103 cells/μL than those without diabetes having serum albumin levels (1.24 ± 0.14) g/dl and platelet counts (58.36 ± 1.634) × 103 cells/μL." (PMID 36268329, 2022). "In addition, urinary NGAL (LCN2) levels were higher in patients with type 2 diabetes than in those without diabetes and higher in patients with urinary albumin than in those without urinary albumin." (PMID 36353239, 2022). "However, the test for interactions was not statistically significant for age, sex, hypertension, diabetes mellitus, albumin, creatinine, killip grade, and culprit vessels (p values for interactions were larger than 0.05)." (PMID 34894008, 2022). "The study model was adjusted for age, sex, baseline eGFR, urine albumin to creatinine ratio, diabetes mellitus, prevalent cardiovascular disease, LDL-cholesterol, HDL-cholesterol, smoking, body mass index, systolic and diastolic blood pressure, C-reactive protein and serum albumin." (PMID 36291168, 2022). "Hypochlorite modified albumin (ALB) is an active compound that is formed during the reaction between proteins, and was found to be much higher in concentration and to act as a mediator of oxidative stress and inflammation in patients with uremia or diabetes mellitus." (PMID 36064366, 2022).
diabetes (continued). "However, most studies did not collect related data such as albumin level or comorbidities such as diabetes or hypertension." (PMID 35205691, 2022). "People with or without diabetes mellitus (DM) were eligible provided they had an estimated glomerular filtration rate (eGFR) ≥20 but <45 mL/min/1.73 m2 or an eGFR ≥45 but <90 mL/min/1.73 m2 with a urinary albumin:creatinine ratio (uACR) ≥200 mg/g." (PMID 35238940, 2022). "Surgical site infection is a rare complication in hernia repair surgery, with an incidence of 0.4% (254/57,951) in a large database study; serum albumin was not independent of diabetes, body mass index >35, and smoking as a predictor of the risk of this complication." (PMID 33925831, 2021). "The negative correlation of SUCR was identified with urinary albumin, diabetes, age, diuretic use, NYHA class, sex, and fibrinogen levels in GISSI–HF and with serum urea nitrogen, peripheral oedema above the ankles, presence of orthopnea, plasma NTproBNP, and female sex in BIOSTAT–CHF." (PMID 34836249, 2021). "The other clinical parameters including age, albumin, tumor location, M stage, total dose > 60 Gy, single dose, GTV volume, chemotherapy, treatment response (PR+CR vs. SD+PD), smoking history, diabetes, and hypertension were not significant for their association with EF." (PMID 35117991, 2021). "In model 2, after adjusting for model 1 plus diabetes mellitus, LVEF, anemia, trace urinary albumin and positive urinary albumin remained associated with increased risk of CIN non-recovery, the OR values were 2.88 (95% CI 1.14–7.11, P = 0.022) and 2.99 (95% CI 1.17–7.56, P = 0.021), respectively." (PMID 33675474, 2021). "Notably, participants enrolled in our study were not limited to diabetic participants but also included those with pre-diabetes or were normoglycemic, and the negative correlation between HbA1c and albumin was shown in all groups." (PMID 34055818, 2021). "Subgroup analyses demonstrated that the association of high serum adiponectin with increased risk of fatal and non-fatal CV events is not modified by age, gender, history of diabetes, estimated glomerular filtration rate (eGFR), or spot urine albumin-to-creatinine ratio (ACR)." (PMID 35097010, 2021). "Previous research has shown increased oxidation of serum Cys34 albumin in acute-on-chronic liver failure, liver cirrhosis, chronic renal failure, and diabetes mellitus, but these studies did not examine whether there were concomitant changes in tissue." (PMID 34439489, 2021). "However, the backward stepwise regression model showed that dp-ucMGP was not an independent determinant of CAC or AVC; instead determinants of CAC included older age, and diabetes (pseudo r2 = 0.45) and determinants of AVC were older age, lower albumin and beta-blocker use (pseudo r2 = 0.29)." (PMID 33626087, 2021). "Several studies on omega-3 polyunsaturated FA supplementation report beneficial effects on urinary albumin excretion and kidney function in patients with and without diabetes, possibly by decreasing inflammation and endothelial dysfunction, as well as reducing hypertension and dyslipidemia." (PMID 34064372, 2021). "With regards to co-existing comorbidities and nutritional status, neither diabetes mellitus (p=0.200), active malignancy (p=0.094) nor pre-operative albumin levels (p=0.151) demonstrated statistically significant differences between infected and non-infected cases." (PMID 32232596, 2020). "However, other notable variables of appreciable accuracy were markers of diabetes control (FBS, RBS) inflammation (CRP), kidney function (potassium, BUN, creatinine and urinary albumin), haematological markers (haematocrit), and systolic blood pressure, among others." (PMID 33198349, 2020). "Despite rigorous attempts to control blood glucose levels based on glycated albumin measurements and the lack of evidence that one test method is superior to the other, the complications of diabetes may progress during pregnancy." (PMID 36312310, 2020).
diabetes (continued). "In single factor analysis, patients with high score of NRS-2002, high score of PG-SGA, diabetes, perioperative blood transfusion, postoperative diarrhea, later tumor stage, high score of ASA, low postoperative albumin, and rectal cancer patients with tumor close to the anus may led to AL." (PMID 32461995, 2020). "In addition, our study found that the levels of total protein, albumin, prealbumin and haemoglobin are significantly lower in patients with diabetes compared to individuals without diabetes, which means diabetes patients are more likely to be undernourished." (PMID 32233013, 2020). "Compared with those without diabetes, cancer patients with diabetes had a larger body mass yet lower muscle strength, poorer performance status and higher incidence of malnourishment, which was accompanied by a decreased level of albumin." (PMID 32813914, 2020). "Moreover, the application of dexamethasone in patients with diabetes or impaired glucose tolerance maintained the beneficial effects, and there was no significant change in either hemoglobin A1c or glycol-albumin over the course of 12 weeks." (PMID 33217828, 2020). "Inflammation is one of the contributing factors in developing diabetes as demonstrated by higher levels of SAA and several other inflammatory markers such as TNF, C-reactive protein (CRP), and MCP-1 that parallel increased urinary albumin secretion in such subjects." (PMID 32075280, 2020). "Subgroup analysis showed that the risk of CVD death rose with a higher LDL-C/HDL-C ratio among PD patients who were female, younger than 65 years old, without being malnourished (BMI ≥ 18.5 kg/m2 or albumin ≥35 g/L), and with a history of diabetes or CVD, respectively." (PMID 32199459, 2020). "To further elucidate the role of circulating albumin in T2D, we conducted a series of related investigations in American Indians who were from a community in the Southwestern United States and were without diabetes." (PMID 30774722, 2019). "We conclude that conditioning on eGFR stage and urine albumin levels, knowledge of diabetes status is less important, but we cannot rule out that our study may be under-powered to detect small but real effects on transition rates." (PMID 36225973, 2019). "In addition, hypoglycemic patients had lower albumin levels, lower rates of albumin increase during admission and lower hemoglobin compared to non-hypoglycemic diabetes patients." (PMID 31398808, 2019). "After multivariate analysis, we found that high AoAC, high CTR, young age, diabetes mellitus, low albumin, high UPCR, and not receiving angiotensin converting enzyme inhibitors (ACEI) and/or angiotensin II receptor blockers (ARB) were independently correlated with a larger negative eGFR slope." (PMID 30926946, 2019). "Age, duration of AS, HLA-B27 positivity, the presence of hyperuricemia, hypertension, diabetes or kidney stones, ESR, CRP, serum albumin, triglyceride and total cholesterol, which might be associated with CKD development, were introduced into the multiple logistic regression model." (PMID 31818273, 2019). "Interestingly, glycated albumin was shown to decrease the anti-inflammatory function of HDL and impair the reversed cholesterol transport function, contributing to the development of CVD in patients with diabetes." (PMID 30922315, 2019). "Moreover, some patients with diabetes are known to progress to nephropathy without having increased urine albumin excretion." (PMID 30729117, 2018). "Moreover, urine albumin, uACR, urine NGAL and NGAL/creatinine ratio, urine transferrin, urine IgG, urine uromodulin, and uromodulin/creatinine ratio significantly correlated with diabetes control as reflected by HbA1c concentrations." (PMID 30158836, 2018).
diabetes (continued). "Adherence to diabetes complication screening was below recommended benchmarks for both HIV+DM and DM-controls for annual foot examination (53 vs. 67%, respectively), biennial eye examination (83 vs. 77%, respectively; and annual urinary albumin measurement (77 vs. 67%, respectively)." (PMID 30429826, 2018). "Because albumin has a half-life of approximately 3 weeks, the plasma fructosamine concentration reflects relatively recent changes in blood glucose and is therefore not commonly used to monitor diabetes treatment." (PMID 28360826, 2017). "Although dysregulated lipid metabolism results in diabetic nephropathy (DN) development in patients with type 2 diabetes mellitus (T2DM), it is not understood whether betatrophin is associated with urinary albumin excretion and renal function." (PMID 26739836, 2016). "Regardless of higher risks of mortality and ESRD in diabetes, the relative risks of these outcomes by eGFR and Albumin-to-Creatinine Ratio (ACR) are much the same irrespective of the presence or absence of diabetes, highlighting the significance of kidney disease as a predictor of clinical outcomes." (PMID 27703559, 2016). "The diabetes patients were classified into those without proteinuria, with microalbuminuria, and with clinical proteinuria groups according to the ratio of urinary excretion of albumin/creatinine (ACR)." (PMID 26517838, 2015). "Moreover, significant differences were observed in age at baseline examination, sex, BMI, social class, hypertension and diabetes mellitus of three study arms i.e. normal albumin excretion, high-normal albumin excretion and microalbuminuria." (PMID 24465635, 2014). "In addition, no study has examined the thresholds of glycated albumin (GA) and 1,5-anhydroglucitol (1,5-AG) for diagnosing diabetes using the presence of diabetic retinopathy (DR)." (PMID 24533962, 2014). "Additionally, individuals with diabetes were significantly older, with greater proportion of CVD, and lower levels of serum albumin than those without diabetes, which have been reported as independently factors responsible for the poor outcomes." (PMID 25329459, 2014). "On the contrary, we did not observe any significant association between plasma concentrations of this uremic toxin and either urine volume, rGFR, total Kt/V, total clearance, nPCR, presence or absence of diabetes, serum albumin, serum phosphate and serum iPTH concentrations." (PMID 24015307, 2013). "The significant correlates were systolic blood pressure (SBP), C-reactive protein (CRP), uric acid, diabetes, gamma-glutamyl transferase (GGT) (marginally significant, p = 0.054) and serum albumin (negative association) for ACR 17+ (mg/g) for men and 25+ for women." (PMID 23947772, 2013). "Extravasation of albumin was markedly attenuated in the diabetic NOX2-/-→WT and WT→NOX2-/- chimeras, suggesting that NOX2 activation in both resident retinal cells and bone marrow derived cells is required for diabetes induced breakdown of the blood-retinal barrier." (PMID 24358357, 2013). "This may contrast to some previous studies showing alleviation of microalbuminuria by metformin in diabetes patients and animal models, although a beneficial effect of metformin on albumin excretion has not been consistently demonstrated." (PMID 24308370, 2013). "In those with MMSE >= 26: Age, sex, education, history of hypertension, diabetes, cerebrovascular disease, heart failure, chronic coronary disease, COPD, hypothyroidism, chronic renal failure, high white blood cells, high blood sedimentation rate, low albumin, low BMI." (PMID 18691409, 2008). "When starting treatment right after induction of diabetes, nitrendipine significantly reduced urinary albumin excretion (UAE) to the nondiabetic level (P < .05) without reducing blood pressure (BP), whereas enalapril failed to significantly reduce UAE despite a reduction in BP." (PMID 15061647, 2003).
diabetes (continued). "Furthermore, it is important to note that many indicators used to evaluate the clinical prognosis of diabetes have incorporated serum albumin in their assessments, such as red blood cell distribution width (RDW)-to-albumin ratio (RAR), neutrophil percentage-to-albumin ratio (NPAR), and so on." (PMID 40013151, 2025). "This outcome in diabetes-specific ONS may also be related to increased energy storage and the increase in carbohydrate consumption resulting from the diet, and the evidence of elevated albumin levels and increased arm and brachial circumferences, without a corresponding effect on muscle mass." (PMID 41156461, 2025). "Additionally, after adjusting for age, sex, subtype, BMI, disease duration, total UMSARS score, OH, diabetes, hypertension, albumin, TG, HDL-C and LDL-C, the RCS analysis showed a non-linear relationship between serum TC level and survival with the lowest risk of death at the value of 4.38 mmol/L." (PMID 41229543, 2025). "In addition, the levels of albumin (ALB), alanine aminotransferase (ALT), aspartate aminotransferase (AST), gamma-glutamyl transferase (GGT), alkaline phosphatase (ALP) and activated partial thromboplastin time (APTT) were lower in the retinopathy group than in the diabetes alone group." (PMID 40589972, 2025). "Although we have shown that the activity of some antioxidants (and others not) bound to albumin may differ in healthy individuals and those with diabetes, the result cannot be interpreted in isolation and without consideration of the entire metabolic mechanism." (PMID 41321387, 2025). "Hierarchical smooth curve fitting showed that serum albumin and CHD risk showed an inverted U-shaped relationship in men, a nonlinear relationship in the participants under 60 years of age, and an approximate negative correlation independent of diabetes status." (PMID 36635398, 2023). "Considering that in diabetes and after prolonged starvation mobilized lipid is mainly transported in the form of plasma albumin-bound fatty acids, rather than TG, these results suggest that ACOT12 and ACOT8 might be required for rapid degradation of fatty acids in these cases." (PMID 37902629, 2023). "Moreover, glycated-ALB serves as a high affinity binding protein for SARS-CoV-2 spike proteins, and this may contribute to immune evasion and influence the severity and the pathology of SARS-CoV-2 infection, especially in prediabetes and diabetes." (PMID 37762957, 2023). "Fifth, diagnosing nephropathy based on measurements of eGFR and ratio of albumin to creatinine in the urine may identify individuals whose nephropathy is unrelated or not exclusively related to prediabetes or diabetes but developed because of other reasons (eg, hypertension)." (PMID 36848190, 2023). "Also, although albumin/creatinine ratio (ACR) is widely used to assess kidney function and diagnose diseases such as CKD, cardiovascular disease and diabetes, this parameter was not used in this study as urine albumin was only available for 28% of the UK Biobank imaging cohort." (PMID 38057740, 2023). "This study evaluated the relationship between urinary albumin-to-creatinine ratio (uACR) and diabetes among adults in the United States of American for the first time, and found that a positive correlation between uACR and diabetes only existed among male participants but not in female participants." (PMID 36175972, 2022). "Compared with low HDL concentration, people with high HDL concentration may be female, non-Hispanic White, married, higher PIR, lower BMI, well-educated, no diabetes, no hypertension, non-work activity, no cardiovascular disease, no smoking, and low albumin/urine." (PMID 35782949, 2022). "Therefore, we found that hypoalbuminemia was an independent risk factor for CKD progression regardless of whether the patients had diabetes mellitus, indicating the importance of serum albumin level for CKD progression." (PMID 36046149, 2022).